MBL1P (mannose binding lectin 1, pseudogene)
Synonyms: COLEC3P; formerly MBL1P1
Gene: Transcribed unitary pseudogene on chromosome 10 (79,920,327 to 79,923,032, forward strand). Ensembl gene ENSG00000242600.
Diseases named in the same sentence as MBL1P in open-access papers:
MBL1P is named in the same sentence as 3 diseases in open-access papers, as found by Europe PMC text mining. Sharing a sentence is not in itself a finding about the gene and the disease. The quoted sentences say what the papers report.
colorectal cancer (1 paper, 2024). A primary or metastatic malignant neoplasm that affects the colon or rectum. "Within the top five genes based on WRF (Ensemble 1 and Ensemble 2), SLC30A3, MOS, C1ORF61, and MBL1P genes were found to have an association with CRC, gene PAGE2, a gene from cancer-germline genes, was found to be upregulated in Caco-2 colorectal cancer cell line." (PMID 39897528, 2024).
coronary artery disease (1 paper, 2024). "In addition, the nearest genes or expression quantitative loci (eQTL) genes in seven loci were previously associated with SU-associated traits, such as ADAMTS9 associated with coronary artery disease and MBL1P associated with COPD23,24." (PMID 38658550, 2024).
MBL1P also shares sentences with these, for which no sentence is quoted: cancer (1 paper).